ING4 (inhibitor of growth family member 4)
Diseases named in the same sentence as ING4 in open-access papers (continued):
Sharing a sentence is not in itself a finding about the gene and the disease.
pancreatic cancer (6 papers, 2013 to 2022). "In addition, miR-214 has been implicated in pancreatic cancer, affecting tumor growth and the response of cancer cells to chemotherapy by targetting ING4." (PMID 30643005, 2019). "In this study, we constructed a novel oncolytic vaccinia virus expressing ING4 (VV-ING4), and evaluated its therapeutic efficacy alone or in combination with gemcitabine against pancreatic cancer cells in vitro and in vivo." (PMID 29137298, 2017). "We verified significant expression of ING4 gene in pancreatic cancer cells after infection with VV-ING4 using qPCR and western blot." (PMID 29137298, 2017). "We also found that ING4 expression induces significant cell cycle arrest in pancreatic cancer cells." (PMID 29137298, 2017). "We found that VV-ING4 significantly increases ING4 expression, displayed greater cytotoxic efficiency, and induced pancreatic cancer cell apoptosis and G2/M phase arrest." (PMID 29137298, 2017). "ING4 expression induced significant apoptosis in SW1990 human pancreatic cancer cells, consistent with the findings of previous studies." (PMID 29137298, 2017). "In this study, we constructed an oncolytic vaccina virus expressing tumor suppressor ING4 (VV-ING4) and revealed that ING4 expression exhibits anti-tumor effects alone and in combination with gemcitabine against pancreatic cancer cells in vitro and in vivo." (PMID 29137298, 2017). "A novel oncolytic vaccinia virus harboring ING4 (VV-ING4) also exhibits great cytotoxic efficiency, by induction of cell cycle arrest and apoptosis in pancreatic cancer cells, amongst others; the combination of VV-ING4 and gemcitabine demonstrates synergistic effects in vitro and in vivo." (PMID 30643005, 2019). "Furthermore, oncogenic Ras regulates the ING4–thymine-DNA glycosylase (TDG)–Fas axis to trigger apoptosis in pancreatic cancer cell lines." (PMID 30643005, 2019). "In this study, we constructed a novel oncolytic vaccinia virus harboring the inhibitor of growth family member 4 gene (VV-ING4) to investigate its therapeutic efficacy alone or in combination with gemcitabine against pancreatic cancer cells in vitro and in vivo." (PMID 29137298, 2017). "Therefore, ING4-induced upregulation of p21 may contribute to the G2/M cell cycle arrest in VV-ING4-treated human pancreatic cancer cells." (PMID 29137298, 2017). "In addition, miR-214 expression was elevated in pancreatic cancer tissues compared with matched benign pancreatic tissues, and overexpression of miR-214 could decreased the sensitivity of the pancreatic cancer cells to gemcitabine by targeting ING4 mRNA." (PMID 23834902, 2013). "Despite its potential as a cancer therapy, the role of VACV-mediated ING4 gene therapy for human pancreatic cancer has not been reported." (PMID 29137298, 2017).
colorectal cancer (4 papers, 2016 to 2023). A primary or metastatic malignant neoplasm that affects the colon or rectum. "In RKO cells, a human colorectal cancer cell line, ING4 overexpression resulted in a decreased population of cells in the S phase and increased proportion of cells in G1/S and G2/M phases." (PMID 30643005, 2019). "Here, we investigated the clinical value of ING4 and its impact on angiogenesis in colorectal cancer (CRC)." (PMID 27806345, 2016).
lymph node metastasis (4 papers, 2016 to 2020). "The data revealed that ING4 expression was significantly negatively associated with the lymph node metastasis and TNM stages (P < 0.001)." (PMID 27806345, 2016). "Moreover, low ING4 expression was significantly associated with increased lymph node metastasis, advanced TNM stage and poor overall survival." (PMID 27806345, 2016). "ING4 expression also correlated with lymph node metastasis in lung, colorectal, ovarian, and clear-cell renal carcinomas and was implicated in prostate epithelial cell differentiation, where loss of ING4 increased the levels of myc-induced prostate oncogenesis." (PMID 31752342, 2019). "In accordance, ING4 expression was found to be lower in grade III than in grade I or grade II tumors, and reduced ING4 mRNA expression correlated with lymph node metastasis as well." (PMID 31390718, 2019). "The univariate Cox regression analysis showed that gender, lymph node metastasis, depth of invasion, distant metastasis, TNM stage and ING4 expression, except for age, histological type and tumor diameter, were the prognostic factors for the CRC patients." (PMID 27806345, 2016).
breast tumors (3 papers, 2012 to 2024). "We proceeded to evaluate ING4 protein expression with the anti-ING4 antibody in breast tumor samples using immunohistochemistry on tumor tissue microarrays (TMAs)." (PMID 23056468, 2012). "In order to evaluate ING4 protein expression in breast tumors, we first generated a monoclonal antibody that recognized endogenous ING4 protein with specificity." (PMID 23056468, 2012). "We surveyed primary breast tumor samples for ING4 protein expression using tissue microarrays and a newly generated antibody." (PMID 23056468, 2012). "We next examined the relationship between low ING4 expression and breast tumor recurrence using the GDS806 dataset." (PMID 23056468, 2012). "In a previous study, we reported that the ING4 gene was deleted in 16.5% of breast tumors." (PMID 23056468, 2012). "Supportive of the ING4 function in the regulation of NF-κB-target gene expression, we found that ING4 expression levels inversely correlated with the expression of NF-κB-target genes in primary breast tumors by analyzing public gene expression datasets." (PMID 23056468, 2012). "We next tested whether low ING4 expression correlated with NF-κB activation in breast tumors by staining the TMAs with an antibody against the p65/RelA subunit phosphorylated at the amino acid residue serine 276 (p-p65/RelA), an activated form of NF-κB." (PMID 23056468, 2012). "The results showed that ING4-low tumors had a mean ING4/NF-κB gene score of 14.8, whereas ING4-high tumors had a mean gene score of 10.2 (p = 0.0002), indicating that ING4-low breast tumors expressed high levels of NF-κB-target genes compared to ING4-high tumors." (PMID 23056468, 2012). "Although we could not assign statistical significance likely due to the small cohort size, these data showed a consistent trend that more advanced breast tumors expressed low levels of ING4." (PMID 23056468, 2012). "In addition, these data also suggested that breast tumors with low ING4 expression would express high levels of NF-κB-target genes." (PMID 23056468, 2012). "In addition, breast tumors expressing low levels of the ING4 protein were frequently high grade and lymph node positive." (PMID 23056468, 2012). "To determine whether ING4-low breast tumors expressed high levels of the 27 NF-κB-target genes we identified above, we evaluated the GDS806 dataset." (PMID 23056468, 2012). "We examined an independent breast tumor gene expression dataset, GSE3521/GPL887, which contained the information on all 27 NF-κB-target genes repressed by ING4." (PMID 23056468, 2012). "Neither the molecular basis for the elevated ING4 gene deletion rate in HER2+ breast tumors nor the epigenetic mechanisms of ING4 down-regulation in breast tumors are known." (PMID 23056468, 2012).
ovarian carcinoma (3 papers, 2013 to 2016). A malignant neoplasm originating from the surface ovarian epithelium. "Based on these encouraging data we constructed Ad5/3∆24 CRAd derivatives armed with IL-24 or ING4 gene and tested their oncolytic potency in human ovarian cancer cell lines and immortalized normal ovarian surface epithelial cells." (PMID 27349517, 2016). "The generated CRAd-IL24 and CRAd-ING4 vectors were tested in ovarian cancer cell lines in vitro to compare their replication, yield, and cytotoxic effects with control CRAd Ad5/3∆24 lacking the therapeutic gene." (PMID 27349517, 2016). "The generated CRAd-IL24 and CRAd-IN4 were tested along with control CRAd vector to validate hypothesis that arming Ad5/3Δ24 with IL-24 or ING4 therapeutic payload may improve oncolytic CRAd potency following infection ovarian cancer cells in vitro and in vivo." (PMID 27349517, 2016). "To determine whether arming with IL-24 or ING4 therapeutic genes leads to improved oncolytic CRAd potency we tested cell viability and cytotoxicity following infection of normal and ovarian cancer (OvCa) cells." (PMID 27349517, 2016). "Overall, these studies revealed that oncolytic potency of CRAd-IL24 is significantly increased as compared to control CRAd and CRAd-ING4 thus, providing a strong rationale for further preclinical testing of CRAd-IL24 therapeutic utility against carcinoma of the ovary." (PMID 27349517, 2016).
B-cell chronic lymphocytic leukemia (2 papers, 2019 to 2022). "A recent study in chronic lymphocytic leukemia cells indicates that the altered expression level of ING4 contributes to regulation of the cell cycle, thereby disrupting mitosis." (PMID 30643005, 2019). "miR-650 on chromosome 22 is located in the Ig λ light chain locus (IgL) and increased expression in B cell chronic lymphocytic leukemia (B-CLL) predicts a more favorable disease course and targets CDK1, ING4 and EBF3." (PMID 35202088, 2022).
cryptogenic organizing pneumonia (2 papers, 2009 to 2019). Cryptogenic organizing pneumonia (COP) is a form of idiopathic interstitial pneumonia characterized pathologically by organizing pneumonia (OP) that presents with non-specific flu-like symptoms, as well as cough and dyspnea and where no etiological agent is found. "The aim of our study was to investigate the role of ING4 in the pathogenesis of pulmonary fibrosis both in the bleomycin (BLM)-model and in two different types of human pulmonary fibrosis, including idiopathic pulmonary fibrosis (IPF) and cryptogenic organizing pneumonia (COP)." (PMID 19250543, 2009).
hypopharyngeal cancer (2 papers, 2019 to 2023). Carcinoma, predominantly squamous cell, arising from the epithelial cells of the hypopharynx.
idiopathic pulmonary fibrosis (2 papers, 2009 to 2019). Idiopathic pulmonary fibrosis (IPF) is a nonneoplastic pulmonary disease that is characterized by the formation of scar tissue within the lungs in the absence of any known cause. "Collectively our dataset demonstrates for the first time in the literature down-regulation of ING4 in different forms of pulmonary fibrosis." (PMID 19250543, 2009). "In accordance with results showed in our experimental model of pulmonary fibrosis, Ing4 gene expression was downregulated in four available IPF compared to six controls and four COP whole lung samples." (PMID 19250543, 2009). "In the present study we analyzed, for the first time in the literature, the expression profiles of ING4 in the experimental model of pulmonary fibrosis as well as in patients with two different forms of fibrotic lung disease, IPF and COP." (PMID 19250543, 2009). "ING4 was found downregulated in both mRNA and protein level within fibrotic lungs compared to controls whereas a gradual decline of ING4 expression following disease progression was noticed in the experimental model of pulmonary fibrosis." (PMID 19250543, 2009). "Although speculative, it is reasonable to assume that ING4 is reduced in more progressive and irreversible forms of pulmonary fibrosis and its suppression may abrogate its versatile protective properties contributing to rapid disease progression and poor treatment responsiveness." (PMID 19250543, 2009). "Interestingly, we noticed a significant down-regulation of ING4 expression, both in mRNA and protein level, in the BLM-model of pulmonary fibrosis compared to untreated mice." (PMID 19250543, 2009).
metastatic melanoma (2 papers, 2012 to 2021). A melanoma that has spread from its primary site to another anatomic site. "The classification tree results of primary and metastatic melanoma showed that ING4 and Cul1 were on the top of tree structure." (PMID 23028750, 2012). "We analyzed primary and metastatic melanomas separately, the ING4 and Cul1 were the best in the classification tree." (PMID 23028750, 2012). "For example, the reduced expression of ING1b and ING4 has been observed in metastatic melanoma and reduced ING4 expression could be correlated with the human gastric adenocarcinoma stage." (PMID 34493070, 2021).
Granuloma (1 paper, 2012). A compact, organized collection of mature mononuclear phagocytes, which may be but is not necessarily accompanied by accessory features such as necrosis. "Our data suggest an impairment of the HIF-1a – VEGF axis, potentialy arising by ING4 overexpression and ultimately resulting in angiostasis and monocyte recruitment within granulomas." (PMID 23181555, 2012). "Reduced activity of HIF-1a due to ING4 overexpression may promote an angiostatic environment within granulomas, while VEGF could be responsible for macrophage chemotaxis." (PMID 23181555, 2012).
Hypertension (1 paper, 2024). The presence of chronic increased pressure in the systemic arterial system. "Natriuretic peptide B (NPPB), QPCT, and inhibitor of growth 4 (ING4) were also recognized as having a significant mediating effect on glucosamine intake for hypertension protection." (PMID 39596173, 2024).
laryngeal carcinoma (1 paper, 2022). Carcinoma that arises from the laryngeal epithelium. "In this study, we explored the role of ING4 and OSM on enhanced anti‐tumour activity for human laryngeal cancer in vitro and in vivo and also elucidation of the underlying mechanism." (PMID 35075768, 2022). "This study for the first time demonstrated the clinical value and the role of co‐expressing Ad‐ING4‐OSM in biological function of laryngeal cancer." (PMID 35075768, 2022). "Recombinant Ad‐ING4‐OSM was used to evaluate their combined effect on enhanced anti‐tumour activity in Hep‐2 cells of laryngeal cancer in vivo." (PMID 35075768, 2022). "Moreover, in vitro function assays of co‐expression of Ad‐ING4‐OSM were performed to explore impact of co‐expression of Ad‐ING4‐OSM on biological phenotype of laryngeal cancer cell line, that is Hep‐2 cells." (PMID 35075768, 2022). "This work suggested that co‐expressing Ad‐ING4‐OSM might serve as a potential therapeutic target for laryngeal cancer patients." (PMID 35075768, 2022). "Therefore, co‐expression of Ad‐ING4‐OSM might serve as a novel therapeutic strategy for patients with laryngeal cancer." (PMID 35075768, 2022). "The human laryngeal cancer Hep‐2 cells were infected with Ad, Ad‐ING4, Ad‐OSM and Ad‐ING4‐OSM at 100 MOI and cultured for 48 h." (PMID 35075768, 2022). "The human laryngeal cancer Hep‐2 cells were infected with Ad, Ad‐ING4, Ad‐OSM and Ad‐ING4‐OSM at 10, 25, 50, 75, 100 and 200, respectively, for 48 h, and then examined by fluorescence microscopy." (PMID 35075768, 2022). "In order to prove whether ING4 and OSM have a significant influence on the growth and apoptosis of human laryngeal cancer Hep‐2 cells, we used recombinant Ad vectors for gene transfer." (PMID 35075768, 2022). "Finally, the underlying mechanism of recombinant adenoviruses co‐expression of ING4 and OSM in laryngeal cancer has not been fully clarified in this study." (PMID 35075768, 2022). "However, the role of recombinant adenoviruses co‐expressing ING4 and OSM (Ad‐ING4‐OSM) in anti‐tumour activity of laryngeal cancer has not yet been identified." (PMID 35075768, 2022).
lung disease (1 paper, 2009). "Future prospective studies in patients with different types of fibrotic lung disease searching for Ing4 mutations coupled with experimental data using ING4 knockout mice may provide a way forward." (PMID 19250543, 2009).
medulloblastoma (1 paper, 2019). A malignant, invasive embryonal neoplasm arising from the cerebellum. "Nevertheless, Myc has been shown to bind to the ING4 promoter, suggesting that ING4 is a direct target of Myc in medulloblastoma." (PMID 30643005, 2019).
myeloma (1 paper, 2019). "ING4 is also reportedly involved in the angiogenic switch in the progression of multiple myeloma and affects the production of the proangiogenic molecules IL-8 and osteopontin (OPN) by inhibiting hypoxia inducible factor-1 α (HIF-1α) under hypoxic conditions." (PMID 30643005, 2019). "Consistent with the evidence above, the inhibition of HIF-1α by ING4 leads to decreased IL-8 and OPN-mediated myeloma angiogenesis." (PMID 30643005, 2019).
prostate carcinoma (1 paper, 2024). A carcinoma that arises from epithelial cells of the prostate gland. "Known for its tumor-suppressing capabilities, ING4’s expression is diminished in a significant portion of primary malignancies in prostate cancer." (PMID 38813086, 2024).
sarcoidosis (1 paper, 2012). Sarcoidosis is a multisystemic disorder of unknown cause characterized by the formation of immune granulomas in involved organs. "qRT-PCR was used to assess HIF-1a and ING4 expression in 10 sarcoidosis mediastinal lymph node and 10 control lung samples." (PMID 23181555, 2012). "Furthermore to gain a holistic view regarding the hypoxia-angiogenesis axis within granulomatous lesions in sarcoidosis patients we investigated the expression of HIF-1a repressor gene, ING4." (PMID 23181555, 2012). "It is therefore impossible to conclude a causal-effect relationship between decline of HIF-1a expression and upregulation of VEGF and ING4 since HIF-1a may have been simply consumed and exerted its functions by the time diagnosis of sarcoidosis was established based on tissue findings." (PMID 23181555, 2012).
Sepsis (1 paper, 2025). Sepsis is defined as life-threatening organ dysfunction caused by a dysregulated host response to infection. "Ultimately, 8 key genes were identified: CD160, HELB, ING4, PIP5K1C, SRPRA (HR < 1); and CDCA7, FAM3A, PPP1R15A (HR > 1), and the hub genes showed apparent differences in expression between alive and dead sepsis patients." (PMID 40612938, 2025). "A lactylation-based prognostic model was developed, comprising eight key genes (CD160, HELB, ING4, PIP5K1C, SRPRA, CDCA7, FAM3A, PPP1R15A), and demonstrated strong predictive performance for sepsis outcomes (AUC = 0.78 in the training cohort; AUC = 0.73 in the validation cohort)." (PMID 40612938, 2025).